TIA1 (TIA1 cytotoxic granule associated RNA binding protein)
Description:
RNA-binding protein involved in the regulation of alternative pre-RNA splicing and mRNA translation by binding to uridine-rich (U-rich) RNA sequences. Binds to U-rich sequences immediately downstream from a 5' splice sites in a uridine-rich small nuclear ribonucleoprotein (U snRNP)-dependent fashion, thereby modulating alternative pre-RNA splicing. Preferably binds to the U-rich IAS1 sequence in a U1 snRNP-dependent manner; this binding is optimal if a 5' splice site is adjacent to IAS1 (By similarity). Activates the use of heterologous 5' splice sites; the activation depends on the intron sequence downstream from the 5' splice site, with a preference for a downstream U-rich sequence. By interacting with SNRPC/U1-C, promotes recruitment and binding of spliceosomal U1 snRNP to 5' splice sites followed by U-rich sequences, thereby facilitating atypical 5' splice site recognition by U1 snRNP. Activates splicing of alternative exons with weak 5' splice sites followed by a U-rich stretch on its own pre-mRNA and on TIAR mRNA (By similarity). Acts as a modulator of alternative splicing for the apoptotic FAS receptor, thereby promoting apoptosis. Binds to the 5' splice site region of FAS intron 5 to promote accumulation of transcripts that include exon 6 at the expense of transcripts in which exon 6 is skipped, thereby leading to the transcription of a membrane-bound apoptotic FAS receptor, which promotes apoptosis. Binds to a conserved AU-rich cis element in COL2A1 intron 2 and modulates alternative splicing of COL2A1 exon 2. Also binds to the equivalent AT-rich element in COL2A1 genomic DNA, and may thereby be involved in the regulation of transcription. Binds specifically to a polypyrimidine-rich controlling element (PCE) located between the weak 5' splice site and the intronic splicing silencer of CFTR mRNA to promote exon 9 inclusion, thereby antagonizing PTB1 and its role in exon skipping of CFTR exon 9. Involved in the repression of mRNA translation by binding to AU-rich elements (AREs) located in mRNA 3' untranslated regions (3' UTRs), including target ARE-bearing mRNAs encoding TNF and PTGS2 (By similarity). Also participates in the cellular response to environmental stress, by acting downstream of the stress-induced phosphorylation of EIF2S1/EIF2A to promote the recruitment of untranslated mRNAs to cytoplasmic stress granules (SGs), leading to stress-induced translational arrest. Formation and recruitment to SGs is regulated by Zn(2+) (By similarity). Possesses nucleolytic activity against cytotoxic lymphocyte target cells. [Isoform Short]: Displays enhanced splicing regulatory activity compared with TIA isoform Long.
Synonyms: TIA-1; ALS26; WDM
Tractability: PROTAC: ubiquitination databases record sites on it; its protein half-life has been measured.
Gene: Protein-coding gene on chromosome 2 (70,209,444 to 70,248,761, reverse strand). Ensembl gene ENSG00000116001.
Subcellular location: Nucleus; Cytoplasm; Cytoplasm, Stress granule
Subcellular location (Human Protein Atlas): Nucleoplasm; Cytosol
Pathways (Reactome):
Signal Transduction: FGFR2 alternative splicing
Gene Ontology:
Molecular function: protein binding; RNA binding; mRNA 3'-UTR binding; poly(A) binding; protein-RNA adaptor activity; mRNA 3'-UTR AU-rich region binding; nucleic acid binding
Biological process: protein localization to cytoplasmic stress granule; regulation of alternative mRNA splicing, via spliceosome; regulation of mRNA splicing, via spliceosome; stress granule assembly; apoptotic process; negative regulation of translation; positive regulation of epithelial cell apoptotic process
Cellular component: cytoplasm; cytoplasmic stress granule; cytosol; nuclear stress granule; nucleoplasm; nucleus; ribonucleoprotein complex
Genetic constraint (gnomAD): Loss-of-function variants: 19 observed, 53.95 expected, observed/expected ratio (o/e) 0.35, 90% interval 0.25 to 0.52. The upper end of that interval is the gene's LOEUF score, 0.52, which puts it in group 2 of 6, group 1 being the genes least tolerant of losing a copy. Missense variants: 305 observed, 420.09 expected, observed/expected ratio (o/e) 0.73, 90% interval 0.66 to 0.8. Synonymous variants: 125 observed, 133.76 expected, observed/expected ratio (o/e) 0.93, 90% interval 0.81 to 1.08.
Gene-disease validity (ClinGen):
ClinGen rates the evidence that TIA1 causes each of these diseases.
amyotrophic lateral sclerosis 26 with or without frontotemporal dementia (autosomal dominant): Limited.
Homologues: Orthologues: macaque TIA1 (99% identical), rabbit TIA1 (99% identical), pig TIA1 (98% identical), dog TIA1 (97% identical), guinea pig TIA1 (97% identical), mouse Tia1 (97% identical), rat Tia1 (97% identical), chimpanzee TIA1 (95% identical), tropical clawed frog tia1 (87% identical), zebrafish tia1 (83% identical), zebrafish tia1l (71% identical). Paralogues in human: TIAL1 (77% identical), HNRNPA3 (19% identical), RBM4 (19% identical), RBM19 (19% identical), RBM4B (19% identical), HNRNPA2B1 (19% identical), RBM39 (18% identical), NUCLEOLIN (18% identical), HNRNPD (18% identical), RBM47 (18% identical), A1CF (18% identical), HNRNPDL (18% identical), and 24 more.
Diseases named in the same sentence as TIA1 in open-access papers:
TIA1 is named in the same sentence as 123 diseases in open-access papers, as found by Europe PMC text mining. Sharing a sentence is not in itself a finding about the gene and the disease. The quoted sentences say what the papers report.
amyotrophic lateral sclerosis (27 papers, 2014 to 2026). Amyotrophic lateral sclerosis (ALS) is a neurodegenerative disease characterized by progressive muscular paralysis reflecting degeneration of motor neurons in the primary motor cortex, corticospinal tracts, brainstem and spinal cord. "TIA1 mutation is implicated in the delay of SG disassembly and accumulation of non-dynamic SGs, and it is involved in neurodegenerative diseases, such as amyotrophic lateral sclerosis (ALS)." (PMID 39940786, 2025). "The low complexity domain of TIA1 contains multiple prolines that are mutated in patients with diseases such as Amyotrophic Lateral Sclerosis (ALS) and Fronto-Temporal Dementia (FTD)." (PMID 38161334, 2023). "We recently reported the identification of mutations in the T-cell restricted intracellular antigen-1 gene (TIA1) as a cause of amyotrophic lateral sclerosis (ALS) and frontotemporal dementia (FTD)." (PMID 29216908, 2017). "Genomic variants in TDP-43 and FUS, genes that encode stress granule proteins, were found to cause familial Amyotrophic lateral sclerosis and several other stress granule proteins (TIA-1, G3BP) may also be pathogenic." (PMID 24586208, 2014). "Mutations in prolines residues within the TIA1 PrD are observed in the TIA1 proteins of patients with Amyotrophic Lateral Sclerosis (ALS) and Fronto-Temporal Dementia (FTD)." (PMID 38161334, 2023). "Many proteins (e.g., FUS, TDP-43, TIA1, tau, α-synuclein) associated with Parkinson’s disease or amyotrophic lateral sclerosis (ALS) also undergo LLPS and are constituents of different types of MLOs." (PMID 34884563, 2021). "A human genetics study identified TIA1 mutations in amyotrophic lateral sclerosis (ALS) and frontotemporal dementia (FTD) patients." (PMID 31118942, 2019). "Mutation in T-cell restricted intracellular antigen-1 gene (TIA1) was identified as a cause of amyotrophic lateral sclerosis (ALS) and frontotemporal dementia (FTD)." (PMID 30533570, 2018). "In this study, we investigated the cellular response to various stress conditions in the context of the TIA1 E384K mutation, a founder variant implicated in both Welander distal myopathy (WDM) and amyotrophic lateral sclerosis (ALS)." (PMID 41007432, 2025). "To illustrate this point, we have analyzed mutations in droplet-forming proteins, FUS (G156E, G187S), TDP-43 (A321V, A315T), TAU (P301L), TIA-1 (E384K), hnRNPA2 (D214V, D290V), UBQLN2 (P506T), which are associated with amyotrophic lateral sclerosis (ALS)." (PMID 36416856, 2022). "Mutations affecting several RBPs, including FUS, TDP-43, hnRNPA1, hnRNPA2B1, matrin-3, and TIA1, are linked to amyotrophic lateral sclerosis (ALS), frontotemporal dementia (FTD), multisystem proteinopathy (MSP), and hereditary inclusion body myopathy (hIBM) phenotypes." (PMID 34291734, 2021). "TIA1 mutations were recently detected in amyotrophic lateral sclerosis (ALS)/frontotemporal dementia (FTD), but a subsequent study suggested exerting caution on the causality of the TIA1 variants in ALS." (PMID 29599744, 2018). "Missense mutations in the TIA1 gene, responsible for Welander distal myopathy (WDM) and amyotrophic lateral sclerosis (ALS), are characterized by delayed SG disassembly and accumulation of non-dynamic SGs that harbor cytotoxic TAR DNA-binding protein 43 (TARDBP, TDP43)." (PMID 35205152, 2022). "TIA1 co-localizes with neuropathology in brain tissue of subjects with AD, frontotemporal lobar dementia, and amyotrophic lateral sclerosis, as well as in animal models of these diseases, all of which are associated with pathological tau misfolding and aggregation." (PMID 32677993, 2020). "Mutations in the stress granule protein T-cell restricted intracellular antigen 1 (TIA1) were recently shown to cause amyotrophic lateral sclerosis (ALS) with or without frontotemporal dementia (FTD)." (PMID 29216908, 2017).
amyotrophic lateral sclerosis (continued). "Genetic analyses of patients with amyotrophic lateral sclerosis (ALS) have revealed a strong association between mutations in genes encoding many RNA-binding proteins (RBPs), including TARDBP, FUS, hnRNPA1, hnRNPA2B1, MATR3, ATXN2, TAF15, TIA-1, and EWSR1, and disease onset/progression." (PMID 32547363, 2020). "For example, as components of SGs, ATX1, hnRNPA1, TDP-43, TIA1, and TAF15 can lead to the occurrence of neurodegenerative diseases such as Alzheimer’s disease (AD), amyotrophic lateral sclerosis (ALS), and frontotemporal dementia (FTD)." (PMID 37179344, 2023). "Aggregation of many RBPs, such as TIA-1, FUS, TDP43, hnRNPA1 and hnRNPA2 in Amyotrophic lateral sclerosis/frontotemporal dementia (ALS/FTD) proteinopathies are mediated by prion-related domain (PRD)." (PMID 30367664, 2018).
lymphoma (23 papers, 2009 to 2025). A malignant (clonal) proliferation of B- lymphocytes or T- lymphocytes which involves the lymph nodes, bone marrow and/or extranodal sites. "By contrast, tumor-infiltrating TIA-1+ cells are associated with decreased survival in lymphoma." (PMID 19641607, 2009). "The co-expression of cytotoxic molecules (TIA-1, Granzyme B) definitively classifies this lymphoma as deriving from a cytotoxic T-cell subset." (PMID 41357592, 2025). "This lymphoma expresses GzB in cytotoxic granules along with perforin and T cell-restricted intracellular antigen-1 (TIA-1)." (PMID 25168906, 2014). "The lymphoma cells displayed a CD3ε/CD56/TIA-1/granzyme-B/Perforin-positive and CD20/CD79a/CD4/CD8-negative immunophenotype and positive for Epstein-Barr virus by EBER in situ hybridization." (PMID 24886075, 2014). "CBCL and CTCL patients who responded had an increase in frequency of CD8+ cells and TIA-1+ cells, indicative of an immune response which is a critical component in the antitumor response in lymphoma." (PMID 24063735, 2013). "These markers as well as TIA-1 and CD8 are routinely used in diagnostic pathology, the latter two for T-cell lineage determination and subtyping of lymphomas thus supporting their value as reliable research tools as well." (PMID 21179245, 2010). "Furthermore, the expression of CD3, CD56, TIA-1 and Granzyme B differentiates NK/T-cell lymphoma from other types of lymphoma." (PMID 25013513, 2014). "TiA1 positive cells were scattered in the lymphoma or in foci." (PMID 19623262, 2009). "Here, we show that lymphoma samples contain cytotoxic CD4+ T cells, which were predominantly NKG7/TIA-1+GZMK+ TFH-like in FL and TIA-1+GZMK+ and/or GZMB+ within the CXCR5+PD-1+ and CXCR5–PD-1+ subpopulations of DLBCL." (PMID 41030456, 2025). "PTCL-NOS with large cells is CD3+, and NK/T-cell lymphoma shows angiocentricity with necrosis with lymphoma cells positive for CD3, CD8, CD56, and cytotoxic markers (TIA-1, granzyme-B, perforin)." (PMID 37958219, 2023). "PTCL-NOS is CD3+ in small and large cells, and NK/T-cell lymphoma shows angiocentricity with necrosis with lymphoma cells positive for CD3, CD8, CD56, and cytotoxic markers (TIA-1, granzyme-B, perforin)." (PMID 37958219, 2023). "Immunohistologically, lymphoma cells in all nine MEITL patients were CD3+, CD8+, and TIA-1+, and eight (89%) were CD56+." (PMID 33087157, 2020). "Based on these results, we determined that this lesion in the appendix was a lymphoma consisting of a diffuse infiltration of primary CD4- and TIA-1-positive cytotoxic T (Th1) cells." (PMID 23302373, 2013). "To assess the cytotoxic potential of TFK cells, we performed a killing assay using FACS-sorted CD19+ B cells (predominantly malignant lymphoma cells) and co-cultured with either CD4+PD-1+CXCR5+TIA-1– TFH or CD4+PD-1+CXCR5+TIA-1+ TFK FACS-sorted from FL and DLBCL samples." (PMID 41030456, 2025). "Microscopic features of ENK/T lymphoma are diverse and the recognition of atypical lymphoid cells and angioinvasion, a broad panel of immunohistochemistry, especially TIA-1, CD56, the cytoplasmic stain of CD3, and EBER ISH, is important to establish a definite diagnosis of ENK/T lymphoma." (PMID 36135102, 2022). "SPTCL is distinct from primary cutaneous γ/δ T-lymphomas, which are typically CD4-, CD8-, CD56+, granzyme B+, perforin+, TIA1+, may involve the epidermis and/or dermis, may present with panniculitic pattern and invariably have a very poor prognosis." (PMID 31311562, 2019). "The lymphoma cells were small to medium-sized and resulted as positive, in all patients, for CD3, CD2, CD7, and TIA1 and negative for ALK, CD56, CD57, granzyme-B, and Perforin." (PMID 37345080, 2023). "However, considering the findings of TIA-1+, EBER1+ and no TCR rearrangement, we finally diagnosed this lymphoma as extranodal NK/T-cell lymphoma (nasal type)." (PMID 22931631, 2012).
lymphoma (continued). "The pathology report indicated no sign of lymphoma in the left capsule or axillary lymph node; however, the fluid from the area surrounding the left implant showed large atypical cells that were positive for CD30, negative for ALK, and negative for CD2, CD3, CD4, CD7, CD8, CD20, CD56, and TIA-1." (PMID 38256500, 2024).
frontotemporal dementia (21 papers, 2011 to 2025). Frontotemporal dementia (FTD) comprises a group of neurodegenerative disorders, characterized by progressive changes in behavior, executive dysfunction and language impairment, as a result of degeneration of the medial prefrontal and frontoinsular cortices. "In frontotemporal dementia (FTD), mutations can alter the properties of TIA1 protein, a prominent stress granules component, increasing their capacity to phase separate and altering the stress granule dynamics." (PMID 36980167, 2023). "An overview of recently proposed ALS genes that were identified based on rare genetic variants (TBK1, CHCHD10, TUBA4A, CCNF, MATR3, NEK1, C21orf2, ANXA11, TIA1) and their potential relevance to the genetic etiology of frontotemporal dementia have also been described." (PMID 33805659, 2021). "In particular, recent findings have shown that T-cell intracellular antigen 1 (TIA1) and other RBPs interact with hyper-phosphorylated tau and accumulate in tandem with tau pathology in diseases such as Alzheimer’s disease (AD) and frontotemporal dementia (FTD)." (PMID 30068389, 2018). "Genetic analysis of neurodegenerative diseases such as ALS, frontotemporal dementia (FTD), Welander distal myopathy (WDM), and multisystem proteinopathies (MSPs) has revealed that TIA-1 carries disease-associated mutations in its IDP region, the prion-like domain (PLD)." (PMID 41446360, 2025).
tauopathy (20 papers, 2017 to 2026). Neurodegenerative disorders involving deposition of abnormal tau protein isoforms (tau proteins) in neurons and glial cells in the brain. "The inter-relationship between both proteins has also been studied in a murine model of tauopathy, wherein it has been observed that TIA1 and other RBPs associated with SGs form and stabilize oligomeric tau accumulations." (PMID 35163320, 2022). "Taken together these results demonstrate that loss of TIA1 leads to increased microglial reactivity in advanced stages of tauopathy." (PMID 32327969, 2020). "Here we show increased synapse loss in the dentate gyrus of both TIA1 haploinsufficient and TIA1 knockout mice in advanced tauopathy." (PMID 32327969, 2020). "Given our results indicating significantly increased expression of complement component C3 with TIA1 reduction, we next investigated effects of TIA1 haploinsufficiency and TIA1 knockout on synapse loss in tauopathy." (PMID 32327969, 2020). "We recently demonstrated that TIA1 reduction protects against the neurodegeneration associated with tauopathy." (PMID 31875547, 2019). "The work presented above demonstrates that modulation of RBP aggregation by TIA1 reduction partially rescues the dysregulation of RNA splicing that is associated with tauopathy in PS19 mice." (PMID 31875547, 2019). "FUS and TARDBP are FTLD genes, and DDX3X and TIA1 have been implicated in tauopathies." (PMID 37730840, 2023). "In many cases, TIA1-mediated inflammatory responses have pathophysiological consequences associated with disorders such as arthritis, phagocytosis/autophagy, atherosclerosis, angiogenesis, neuroinflammation, obesity, myopathy, tauopathy and cancer." (PMID 35163320, 2022). "Additionally, a TIA1-associated neuronal inflammatory phenotype has been described in tauopathies in the P301S mouse model mediated by a cytotoxic process of the central nervous system via TNF-α, IL-6 and IL1-β." (PMID 35163320, 2022). "We then used an unbiased systems biology approach to identify upstream regulators that might contribute to the transcriptional and splice variant changes in the neuroprotected PS19 Tia1+/− mice compared to the PS19 Tia1+/+ tauopathy mice." (PMID 31875547, 2019). "Thus, whether TIA1 is facilitated in the deterioration of tauopathy caused by anesthesia and surgery still needs more exploration." (PMID 34512311, 2021). "Changes in the expression and/or subcellular localization of TIA1 have been associated with important pathophysiological consequences in human biology and disease, including embryogenesis, inflammation, tumorigenesis, neuronal homeostasis, tauopathies, myopathies, cell stress and viral infections." (PMID 34884582, 2021). "Emerging evidence found that TIA1 reduction increased microglial phagocytosis in advanced tauopathy 57, while a recent study reported that CX3CR1 driven knockout of TIA1 in microglia greatly reduced microglial inflammation 58, aligning with our findings." (PMID 41424856, 2026). "Reducing TIA1 levels in vivo counteracts the tauopathy, protects against neurodegeneration, and prolongs the survival of P301S Tau mice, a model for Alzheimer’s disease." (PMID 41188647, 2025). "Reducing TIA1 levels can inhibit the accumulation of tau oligomers and improve neuronal survival in tauopathy mouse models." (PMID 41188647, 2025). "For instance, reducing TIA1 level offers protection against tauopathy, while mutant FUS drives early FUS ALS neurodegeneration." (PMID 40355949, 2025). "Reduced TIA‐1 expression rescues cognitive decline and increases survival in a mouse model of tauopathy." (PMID 39155453, 2024). "Recently, it has been demonstrated in an AD mouse model that the reduction of TIA1 leads to a delay of degeneration and that the dysregulation of RNA splicing is a relevant pathophysiological mechanism in tauopathies." (PMID 36499709, 2022).